FTSJ3 (FtsJ RNA 2'-O-methyltransferase 3)
Description:
RNA 2'-O-methyltransferase involved in the processing of the 34S pre-rRNA to 18S rRNA and in 40S ribosomal subunit formation. (Microbial infection) In case of infection by HIV-1 virus, recruited to HIV-1 RNA and catalyzes 2'-O-methylation of the viral genome, allowing HIV-1 virus to escape the innate immune system. RNA 2'-O-methylation provides a molecular signature for discrimination of self from non-self and is used by HIV-1 to evade innate immune recognition by IFIH1/MDA5. Mediates methylation of internal residues of HIV-1 RNA, with a strong preference for adenosine. Recruited to HIV-1 RNA via interaction with TARBP2/TRBP.
Synonyms: SPB1; EPCS3
Tractability: Small molecule: a structure with a bound ligand is known. PROTAC: UniProt records ubiquitination sites on it; ubiquitination databases record sites on it; its protein half-life has been measured.
Gene: Protein-coding gene on chromosome 17 (63,819,433 to 63,830,012, reverse strand). Ensembl gene ENSG00000108592.
Subcellular location: Nucleus, nucleolus
Subcellular location (Human Protein Atlas): Nucleoli; Nucleoli rim; Mitotic chromosome
Pathways (Reactome):
Metabolism of RNA: Major pathway of rRNA processing in the nucleolus and cytosol
Gene Ontology:
Molecular function: protein binding; RNA 2'-O-methyltransferase activity; RNA binding; rRNA (guanine) methyltransferase activity; rRNA (uridine-2'-O-)-methyltransferase activity; methyltransferase activity; rRNA methyltransferase activity
Biological process: RNA methylation; maturation of 5.8S rRNA from tricistronic rRNA transcript (SSU-rRNA, 5.8S rRNA, LSU-rRNA); maturation of LSU-rRNA from tricistronic rRNA transcript (SSU-rRNA, 5.8S rRNA, LSU-rRNA); rRNA methylation; rRNA processing
Cellular component: nucleolus; preribosome, large subunit precursor; nucleus; preribosome, small subunit precursor
Genetic constraint (gnomAD): Loss-of-function variants: 46 observed, 116.12 expected, observed/expected ratio (o/e) 0.4, 90% interval 0.31 to 0.51. The upper end of that interval is the gene's LOEUF score, 0.51, which puts it in group 2 of 6, group 1 being the genes least tolerant of losing a copy. Missense variants: 1,063 observed, 1,105.5 expected, observed/expected ratio (o/e) 0.96, 90% interval 0.91 to 1.01. Synonymous variants: 406 observed, 400.3 expected, observed/expected ratio (o/e) 1.01, 90% interval 0.93 to 1.1.
Homologues: Orthologues: chimpanzee FTSJ3 (99% identical), macaque FTSJ3 (96% identical), pig FTSJ3 (88% identical), dog FTSJ3 (88% identical), mouse Ftsj3 (88% identical), rabbit FTSJ3 (88% identical), guinea pig FTSJ3 (87% identical), rat Ftsj3 (86% identical), zebrafish ftsj3 (61% identical), tropical clawed frog ftsj3 (60% identical), Caenorhabditis elegans H06I04.3 (40% identical), Drosophila melanogaster CG8939 (39% identical). Paralogues in human: FTSJ1 (15% identical), MRM2 (8% identical).
Diseases named in the same sentence as FTSJ3 in open-access papers:
FTSJ3 is named in the same sentence as 9 diseases in open-access papers, as found by Europe PMC text mining. Sharing a sentence is not in itself a finding about the gene and the disease. The quoted sentences say what the papers report.
breast carcinoma (2 papers, 2021 to 2022). "Kaplan-Meier analysis revealed that copy number amplification of FTSJ3 is associated with a shorter overall survival time in breast cancer." (PMID 36262473, 2022).
colon cancer (1 paper, 2022). "Our findings indicated that DEDD2, GTF2H5, SNRPA1, BICD1, CELF1, and CLK3 were prognostic risk factors for colon cancer, while ADAD1, CMTR1, HNRNPUL1, FTSJ3, WDR43, THUMPD3, SNRPF were prognostic protective factors." (PMID 36212157, 2022).
rectal cancer (1 paper, 2021). A primary or metastatic malignant neoplasm that affects the rectum. "To validate the hub genes in our data set, we examined the expression level of UTP6 and FTSJ3 by comparing the rectal cancer tissues of CRT-resistant and-sensitive cases using an external dataset." (PMID 34485268, 2021). "To validate the hub genes, we examined the expression of UTP6 and FTSJ3 in rectal cancer tissues of CRT-resistant and CRT-sensitive cases in our datasets." (PMID 34485268, 2021).
uterine corpus endometrial carcinoma (1 paper, 2021). A endometrial carcinoma (disease) that involves the body of uterus. "In addition, 1.26% of patients in the TCGA pan cancer cohort had FTSJ3 mutations, and the mutation frequency was the highest (5.80%) in patients with uterine corpus endometrial carcinoma." (PMID 33752626, 2021).
cancer (2 papers, 2021 to 2024). A tumor composed of atypical neoplastic, often pleomorphic cells that invade other tissues. "The analysis revealed a distinct overexpression of a single isoform for several genes, namely AGBL5, BOP1, FTSJ3, LGALS1, and NOP58, suggesting a dominant role of these isoforms in the cancer phenotype." (PMID 39001461, 2024).
infection (1 paper, 2021). The state of being infected such as from the introduction of a foreign agent such as serum, vaccine, antigenic substance or organism. "FTSJ3 is involved in the processing of 34S pre-rRNA to 18S rRNA and in 40S ribosomal subunit formation and is used by HIV-1 to evade innate immune recognition by IFIH1/MDA5 in cases of infection by HIV-1 virus." (PMID 33752626, 2021).
FTSJ3 also shares sentences with these, for which no sentence is quoted: colorectal cancer (1 paper); tumour (1); viral infection (1).